MTOR (mechanistic target of rapamycin kinase)
Diseases named in the same sentence as MTOR in open-access papers (continued):
Sharing a sentence is not in itself a finding about the gene and the disease.
tumor (continued). "Similarly, DHCR7 (cholesterol biosynthesis), DDIT4 (mTOR regulation under stress), HNRNPAB (RNA splicing), and SLC39A8 (zinc signaling) all reflect well-documented mechanisms of tumor growth or adaptation." (PMID 40941703, 2025). "However, some studies reported that long-lasting exposure to metformin increases the mTOR/HIF-1α pathway and anti-tumor activity in macrophages." (PMID 40806725, 2025). "In this study, we found that rapamycin, at the examined low dosage, targets mTOR in tumor cells without exerting effects on the immune cells, particularly CD8+ T cells, sensitizing RAC1A159V tumors to ICIs." (PMID 41160695, 2025). "An accepted view is that metformin exerts anti-tumor effects through various proposed mechanisms, including the modulation of the cellular AMP/ATP ratio, activation of the AMPK/mTOR pathway, inhibition of mitochondrial complex I, and suppression of gluconeogenesis." (PMID 40430574, 2025). "Specifically, we demonstrated that acetate produced by F. rodentium increases CD8+ T-cell immunity and modulates PDPN/CLEC-2/PI3K/AKT/mTOR signaling by downregulating PDPN expression on CD8+ T cells and CLEC-2 expression on tumor cells, resulting in the inhibition of CRC." (PMID 40693815, 2025). "Binding to the CD36 receptor on tumor cells, oxLDL activates the PI3K/AKT/mTOR pathway, upregulating key glycolytic enzymes (e.g., hexokinase, phosphofructokinase, pyruvate kinase) while stabilizing HIF-1α to enhance glycolysis in both tumor cells and M2-polarized TAMs." (PMID 40563359, 2025). "Although rapamycin inhibits the mechanistic target of rapamycin (mTOR), it is not effective as monotherapy since tumor cells can activate alternative survival pathways, such as AKT signaling." (PMID 40077707, 2025). "Similarly, ECM-receptor interaction is critical for tumor progression, particularly via the PI3K/AKT/mTOR and Ras/MAPK pathways, which regulate cell adhesion, migration, and proliferation." (PMID 41465316, 2025). "Because tumor progression in these models involves a shift from AR-positive CRPC to AR-negative NEPC, we propose that EZH2 and PI3K/mTOR inhibitor co-treatment is particularly effective in castrate conditions due to EZH2 inhibition restoring AR expression and function." (PMID 40832297, 2025). "In vivo, V9302 administration significantly inhibited tumor growth without inducing systemic toxicity, and IHC of the treated tumors confirmed the suppression of the mTOR pathway and induction of apoptosis." (PMID 41514527, 2025). "Our group had previously developed a dual-target PI3K/mTOR inhibitor YYN-37, characterized by notable anti-tumor activities both in vitro and in vivo, good kinase selectivity, minimal hepatotoxic effects, moderate plasma clearance rates, and satisfactory oral bioavailability." (PMID 41471338, 2025). "In contrast, miRNAs downregulated in rKGAS cells were found to regulate tumor suppressor genes such as IGF1R, TNFAIP3, and MTOR, suggesting that the acquisition of chemoresistance may involve altered regulation of both oncogenic and tumor-suppressive pathways." (PMID 40952575, 2025). "Notably, nobiletin suppresses tumor growth by inhibiting SREBP1 nuclear translocation, deactivation of the PI3K/Akt/mTOR pathway, and induction of autophagy-dependent cell death." (PMID 40668814, 2025). "It drives tumor progression through multiple mechanisms: UCA1 can act as a molecular sponge for tumor-suppressive miRNAs, it modulates signaling pathways like mTOR and STAT3 to enhance glycolysis and proliferation, and it interacts with epigenetic regulators to alter gene expression." (PMID 40918525, 2025). "Salirasib exerts its antitumour effects by interfering with the localisation of active Ras proteins to the plasma membrane, thereby attenuating downstream Ras signalling cascades, specifically the PI3K/Akt/mTOR pathways and Raf/MEK/ERK, essential for tumour cell proliferation and long‐term survival." (PMID 41020311, 2025).
tumor (continued). "Subsequently, we investigated whether TRIM17 influences tumor progression by modulating FTO protein expression and regulating the AKT/mTOR signaling pathway." (PMID 41145484, 2025). "It was observed that lycopene treatment for 72 h repressed the proliferation, invasion, and migration of tumor cells as well as suppressing epithelial–mesenchymal transition by down‐streaming N‐cadherin, the PI3K/AKT/mTOR signaling pathway, p‐AKT, p‐PI3K, p‐mTOR, and bcl‐2 levels." (PMID 40661795, 2025). "The tumor suppressor PTEN acts as a negative regulator of the PI3K/Akt pathway, and LoF leads to stable activation of the PI3K/Akt pathway, constantly activating mTOR." (PMID 40165380, 2025). "Regulation of the tumor cell cycle.Inhibition of AML cell proliferation and migration, also as apoptosis induction in cell models including THP1, HL60, MV4-11, etc.↓ phosphorylated AKT and phosphorylated mTOR molecules.↑ drug sensitivity." (PMID 41157107, 2025). "This review highlights the central importance of ROS-regulated signaling pathways—including MAPK/ERK, PI3K/Akt/mTOR, JAK/STAT, NF-κB, HIF-1α, and NRF2—in driving proliferation, survival, metabolic adaptation, immune evasion, and therapy resistance in tumor cells." (PMID 40867898, 2025). "Further experimental validation indicated that ART could inhibit the phosphorylation activity of the PI3K/AKT/mTOR signaling pathway in BLCA cells, effectively suppressing tumor proliferation and survival." (PMID 40303931, 2025). "Tumor DNA from newly acquired biopsies or ctDNA were analyzed for alterations targetable with the PD-L1 inhibitor atezolizumab, the MEK inhibitor cobimetinib, the mTOR inhibitor everolimus, or the PARP-inhibitor niraparib." (PMID 40468525, 2025). "Unlike the xenograft tumors that were treated with a PI3K/mTOR inhibitor, a correlation between tumor biologic behavior and forkhead box O1 immunoreactivity was not present in the patient-derived tumor sections." (PMID 41106249, 2025). "Among them, PI3K/AKT/mTOR and MAPK pathways have been widely proved to be the core targets of CTD against tumor metastasis, and CTD, as a multi-targeted anticancer agent, has demonstrated its unique advantages in inhibiting tumor growth, metastasis, and synergistic radiotherapy." (PMID 41035918, 2025). "Furthermore, Akt/mTOR signaling upregulates vascular endothelial growth factor (VEGF), driving tumor angiogenesis critical for growth, invasion, and metastasis." (PMID 41383608, 2025). "This review describes how autophagy contributes to HCC at different stages, outlines the dual functions of lncRNAs as oncogenic drivers or tumor suppressors, and illustrates their integration into key signaling networks of autophagy (e.g., PI3K/AKT/mTOR, AMPK, Beclin-1)." (PMID 40789840, 2025). "In addition, NRBP2 is suggested as a tumor suppressor by suppressing key oncogenic signaling pathways, such as AKT and Mammalian Target of Rapamycin (mTOR) pathways." (PMID 40645931, 2025). "For example, elevated extracellular levels of potassium, released by necrotic tumor cells into the extracellular fluid of tumor, metabolically reprograms T-cell to induce stemness, self-renewal of T-cells, impairs TCR-driven Akt–mTOR phosphorylation and effector programs." (PMID 40236693, 2025). "In addition, p-AKT/p-mTOR, including the downstream effector p-4E-BP1 and the Ras/MAPK candidate p-ERK1/2, was increasingly expressed in the WT tumor." (PMID 40725179, 2025). "IDET modulates various molecular targets, including NF‐κB, PI3K/AKT/mTOR, Wnt/β‐catenin, STAT3, and MAPK, thereby influencing processes such as apoptosis, autophagy, cell cycle regulation, and cell survival, which in turn affect tumor progression." (PMID 41394539, 2025). "Similarly, mTOR, a downstream target of AKT, is also commonly overexpressed or hyperactivated in OSCC, contributing to tumor development and progression." (PMID 39781358, 2025).
tumor (continued). "Furthermore, we performed immunofluorescence (IF) staining for Ki67, TUNEL assay to detect apoptosis, and Western blot to assess AMPK, mTOR, and SCD1 protein expression in tumour tissues derived from model mice." (PMID 41311830, 2025). "The addition of the mTOR inhibitor rapamycin reduced IL33-induced LD formation and DGAT1/2 and PPARG expression, as well as the survival ability, proliferation ability, and ability to promote tumor cell proliferation of teHDNs." (PMID 41214328, 2025). "Studies have shown that Vorinostat not only activates p21 expression to induce cell cycle arrest and apoptosis, but also interferes with tumour cell proliferation, metabolism, and survival by regulating multiple signalling pathways such as NF‐κB, JAK/STAT, PI3K‐AKT and mTOR." (PMID 41431124, 2025). "Both Nef and K1 activate the PI3K/AKT/mTOR signaling pathway, individually or synergistically, while reducing the level of Phosphatase and Tensin Homolog deleted on chromosome 10 (PTEN), a key tumor suppressor." (PMID 40636501, 2025). "Furthermore, it is observed that the inhibitors against IGF1R or mTOR exhibit suppressive effects on patient-derived tumor xenograft tumors with high IGFRIL expression, through simultaneous blocking of the IGF1R-AKT-mTOR signaling pathway." (PMID 40686314, 2025). "Moreover, AA2 and AA3 affect the Akt/mTOR and STAT‐3 signaling pathways by inhibiting the key cellular processes of cell proliferation, survival, and tumor growth." (PMID 40717210, 2025). "Recent studies suggest that tumor-infiltrating lymphocytes (TILs) may influence hormone receptor expression and activate survival pathways such as PI3K/AKT/mTOR, linking immune infiltration to endocrine resistance." (PMID 40566067, 2025). "This trend is consistent with previous studies, suggesting that HER-2 overexpression may promote tumor cell dedifferentiation and malignant progression by activating downstream proliferative signaling pathways, such as PI3K/AKT/mTOR." (PMID 40678390, 2025). "Not surprisingly, we see a strong upregulation of MAPK and mTOR target expression in the tumor regions at the leptomeninges closer to the tumor-stroma interface." (PMID 38866016, 2024). "Meanwhile, metformin has an anti-tumor effect by activating the AMPK pathway and mTOR inhibition." (PMID 39000600, 2024). "When mTOR was targeted, neither complete nor partial responses were seen, but the median time before disease progression was 11.2 months, and tumor reduction was noted in 44% of the patients." (PMID 38202273, 2024). "HGF is secreted by stromal cells in the tumor microenvironment, and binds to and activates c-MET receptors on the surface of NSCLC cells, initiating a series of downstream signaling pathways such as PI3K/AKT/mTOR, MAPK, and Wnt/β-catenin." (PMID 39201787, 2024). "Notably, even at the early stage of treatment with approximately 30% tumor shrinkage, significant recovery of phosphorylation in AKT/MTOR and MAPK pathways was observed." (PMID 39041204, 2024). "Additionally, in a nude mouse xenograft model (0.5–1 mg/kg, once daily), yuanhuacine significantly reduced tumor growth and weight, possibly through the modulation of AMPK and mTOR signaling pathways." (PMID 38794168, 2024). "After inhibiting the AKT/mTOR pathway, although the drug-resistant mutant (mTorRR) CAR–T cells can be tolerated, bystander immune cell function remains suppressed, thereby impeding tumor cell clearance and potentially compromising therapeutic efficacy." (PMID 39220130, 2024). "In addition to many oncogenic signaling pathways, such as JAK/STAT or PI3K/mTOR, inflammasome activation has long been suggested to promote EMT, leading to tumor growth and progression." (PMID 38254674, 2024). "The examined immunohistochemical localization of mTOR in the OSCC tissue samples showed that there was no apparent correlation between mTOR expression and any clinicopathological characteristic, including the tumor stage, location, and differentiation status." (PMID 38791040, 2024).
tumor (continued). "Hypoxia in glioblatoma associates with complex signaling patterns including activation of several pathways such as MAPK, PI3K-AKT/mTOR and IL-6/JAK/STAT3 with the master regulator HIF-1, which in turn drive particular tumor behaviors determining, in the end, treatment outcomes and patients fate." (PMID 38654280, 2024). "In our study, the introduction of chrysin did not alter the expression of mTOR in tumor cells; conversely, it inhibited the phosphorylation of ULK1, effectively reversing the autophagic activation state in the cells." (PMID 38675475, 2024). "The PI3K/AKT/mTOR pathway plays an important role in EMT and glycolysis of tumor cells." (PMID 38916406, 2024). "We then excised the mouse xenograft tumor tissues and found that the phosphorylation rates of the PI3K-Akt-mTOR signaling pathway constituents and the ASNS expression levels were markedly lower in the neoplasms of the TMEM176B knockdown mice than in those of the control mice." (PMID 38438907, 2024). "Previous studies have found that NEDD9 can activate the AKT/mTOR pathway and affect tumor progression, but no relevant studies have been reported in HCC." (PMID 39060928, 2024). "Furthermore, these phenomena were induced through the activation of the PI3K/AKT/mTOR pathway, and they were observed to enhance the expression of periostin (POSTN) and N-cadherin in the EMT around the tumour tissues." (PMID 39120301, 2024). "The mTOR inhibitor compound RTP had comparable anti-tumor activity to sorafenib in HCC organs, and it was also found that targeting the mTOR pathway could effectively treat acquired sorafenib-resistant HCC organs." (PMID 39062508, 2024). "The binding of IL-17 to IL-17R on tumor cells activates downstream molecules, including transcription factors (NF-κB, STAT, and AP-1), kinases (MAPK and HER1), matrix metalloproteinases (MMPs), and anti-apoptotic proteins (Akt, Erk, mTOR, Bcl-2, and Bax)." (PMID 39205642, 2024). "To obtain a more complete understanding of the varied effects of the respective mTOR-Is + IR, we investigated their impact on the downstream protein S6 by measuring its levels of phosphorylation via the IS of p-S6 in UM-SCC-47 HNSCC tumor cells over a period of 0 to 16 h after IR exposure." (PMID 38391917, 2024). "The correlation between p62 expression and Beclin1/mTOR showed a negative and positive correlation, respectively, confirming autophagy activation in the tumor tissues." (PMID 38164366, 2024). "Thus, BEZ235 plus BMS-1166 inhibited the PI3K/mTOR and MAPK pathways, triggering the mitochondrial apoptotic pathway and thus enhancing the anti-tumor effect of BMS-1166." (PMID 39113885, 2024). "Schisandrin A had an anti-tumor effect, and its mechanism might be related to the inhibition of the PI3K/AKT/mTOR signaling pathway." (PMID 38452391, 2024). "Firstly, the in vivo experiment only observed the pharmacodynamic effect of formononetin on subcutaneous transplanted tumors in nude mice, without utilizing mTOR inhibition to monitor tumor changes." (PMID 39399463, 2024). "All these PI3K isoforms promote tumor cell survival, proliferation and metastasis by regulating different processes including tumor cell metabolism, angiogenesis and by modulating the TME and immunity, mainly via the activation of the AKT/mTOR and the GSK3β/beta-catenin pathways." (PMID 38420122, 2024).
tumor (continued). "Therefore, experiments on the combination of mTOR and GLS inhibitors have been conducted, and they have shown anti-tumor effects in xenograft models." (PMID 38895635, 2024). "Moreover, results of the Western blot analysis of tumor samples indicated that the short-term anti-GPC1 mAb treatment had little effect on the activity of the MEK/ERK/RSK and Akt/GSK3/mTOR pathways." (PMID 38966167, 2024). "mTOR serves as a key substrate for the PI3K/Akt signaling pathway, and its S2448 site can be phosphorylated and activated by AKT, which subsequently regulates tumor cell energy metabolism and triggers processes such as autophagy and apoptosis." (PMID 39881875, 2024). "For example, it was found that combinations of cetuximab and PI3K, AKT, or mTOR inhibitors can profoundly control tumor growth in metastatic CRC regardless of driver genotypes." (PMID 38956060, 2024). "This leads to the activation of NF-κB, a key pro-inflammatory transcription factor, and increased production of pro-inflammatory cytokines, thus creating an inflammatory milieu with tumour-promoting effect, that further triggers signalling pathways, such as MAPK/ERK or PI3K/AKT/mTOR." (PMID 39684475, 2024). "Furthermore, miR-193a-5p suppresses LC metastasis by targeting ERBB4/PIK3R3/mTOR/S6K2, and this tumor suppressor was upregulated in males but downregulated in females." (PMID 38245882, 2024). "As the upstream site of the P13K/Akt/mTOR signaling pathway, the PTEN gene inhibits tumor formation through negative regulation of this signaling pathway, whereas inactivating the PTEN gene reduces the negative regulation of this pathway and causes malignant changes in cells." (PMID 39206155, 2024). "These treatment strategies may involve targeting glucose supply, which can have toxic effects on tumor cells in the hypoxic TME, or inhibiting key enzymes in the glycolytic pathway, including glucose transporters, HIF-1α, and the mTOR pathway." (PMID 39227970, 2024). "Similar to PI3K/AKT/mTOR pathway, NOTCH-signaling promotes communication between adjacent cells in the bone marrow microenvironment and has been shown to be dysregulated in the MM tumor niche." (PMID 39164264, 2024). "Tumor suppressor TRPM4, a calcium-activated nonselective cation channel, inhibits the PI3K/Akt/mTOR signaling pathway to impede tumor migration and invasion." (PMID 38279330, 2024). "The expression of HIF-1α mRNA may be a potential driving factor for tumor growth and metastasis, and HIF-1α is a downstream transcription factor of mTOR." (PMID 38771435, 2024). "These family members are activated by ligand-dependent homo-/heterodimerisation and regulate cellular proliferation and tumour progression via the downstream activation of many commonly used growth factor signalling pathways, such as the RAS/RAF/MEK/ERK and PI3K/AKT/mTOR pathways." (PMID 38787171, 2024). "CAFs have been shown to support tumor cells through exosomal transfer and the paracrine signaling mediated by NF-κB and cytokines such as IL-6, thereby activating the downstream JAK/STAT3, mechanistic target of rapamycin (mTOR), and SHH pathways." (PMID 38318525, 2024). "Inhibition of mTOR by the addition of rapamycin, upregulation of TSC2 or blockade of STAT3 in monocytes/macrophages has been shown to promote the release of M1 cytokines and inhibit tumor growth, which was confirmed by reduced tumor angiogenesis." (PMID 39003350, 2024). "Baicalein dose-dependently upregulated E-cadherin, the cleaved Caspase-3 and downregulated the expression of Vimentin, Snail, MMP2, MMP9, Bcl-2, p-PI3K, p-AKT, and p-mTOR in HGC-27 and SGC-7901 cells, which appeared to inhibit tumor growth in vivo and in vitro." (PMID 39654621, 2024). "Tumor-derived lactate increased the expression of PD-1 on Tbet+NK1.1− ILCs in the TME, which led to an increase in fatty acid metabolism and a reduction in the mammalian target of rapamycin (mTOR) signaling." (PMID 39126091, 2024).